KIT (KIT proto-oncogene, receptor tyrosine kinase)
Diseases named in the same sentence as KIT in open-access papers (continued):
Sharing a sentence is not in itself a finding about the gene and the disease.
Ewing sarcoma (14 papers, 2005 to 2024). A small round cell tumor that lacks morphologic, immunohistochemical, and electron microscopic evidence of neuroectodermal differentiation. "After four years of recurrent episodes and worsening symptoms, an incisional biopsy revealed an Ewing sarcoma with a KIT gene mutation (M541L, on exon 10)." (PMID 38222235, 2023). "The identification of EWS/FLI1 chromosomal translocation and KIT/PDGFR mutations are indispensable in confirming the diagnosis of Ewing's sarcoma and GIST respectively." (PMID 27509178, 2016). "This is also the first report describing the KIT M541L mutation (exon 10) in Ewing sarcoma." (PMID 38222235, 2023). "In this case, the detection of a KIT mutation in an Ewing sarcoma developed at the site of previous mast cell proliferation raises the hypothesis of a possible sarcomatous evolution of the original lesion." (PMID 38222235, 2023). "KIT gene mutations with gain-of-function were identified in 2.6% of Ewing sarcomas." (PMID 38222235, 2023). "In particular, high-grade endometrial stromal sarcomas have round blue cell morphology, may have pseudo rosettes and are commonly positive for CD99, Cyclin D1 and KIT, all of which are also positive in Ewing sarcoma." (PMID 39777304, 2024). "In addition, the resistance of Ewing tumour cells to imatinib mesylate, an inhibitor of c-KIT, suggests that stem cell factor is also not a key survival factor in Ewing tumours." (PMID 15685229, 2005). "Moreover, in the same study, in Ewing sarcoma, exposure to PU-H71 resulted in depletion of critical proteins, including AKT, pERK, Raf-1, c-MYC, c-KIT, IGF1R, hTERT, and EWS-FLI78." (PMID 32895397, 2020).
germinoma (14 papers, 2013 to 2025). A malignant germ cell tumor arising in the central nervous system. "Correlation studies revealed that for germinomas, overexpression of KIT was largely related to KIT/RAS mutations, with the KIT/RAS mutation status exerting a significant adverse effect on patient prognosis." (PMID 38012690, 2023). "In germinoma cases, overexpression of KIT was associated with severe chromosomal instability, with patients exhibiting an unstable chromosomal state demonstrating a significantly worse prognosis." (PMID 38012690, 2023). "Somatic mutations in the CBL gene are frequently encountered in ICGCT and represent another cause of KIT overexpression in germinomas." (PMID 34357128, 2021). "We examined a total of 51 germinomas and 1 mixed GCT (germinoma and teratoma component) for mutations in KIT exons 11, 13, 17 and 18 as well as mutation hotspots in HRAS, KRAS, NRAS and RRAS-2." (PMID 27391150, 2016). "KIT has a high mutation frequency in germinoma, but it was rare in NGGCT." (PMID 36457486, 2022). "Intracranial germinomas present genetic and epigenetic alterations (chromosomal aberrations, KIT, MAPK and PI3K pathways mutations, DNA hypomethylation, miRNA dysregulation) that may represent targets for therapy." (PMID 34357128, 2021). "Therefore, avapritinib may also be a promising therapeutic option for germinomas with KIT mutations." (PMID 32999426, 2020). "Moreover, they assume that gene-specific methylation and additional genetic events, like KIT mutations in germinomas, might play a role in specification of these tumors." (PMID 27391150, 2016). "Various studies have shown that activating mutations in MAPK pathway are common alterations in intracranial GCTs, with KIT expression seen in most germinomas." (PMID 39959669, 2025). "Recurrent somatic mutations in the KIT/RAS/MAPK pathways and AKT/mTOR pathways have been well documented in intracranial GCTs, with KIT/KRAS/MAPK alterations known to be enriched in germinomas." (PMID 39959669, 2025). "Development of targeted therapeutics against KIT has led to the prospect of targeted therapy in germinoma." (PMID 39959669, 2025). "Research indicated that KIT mutations were present in 40% of germinomas and 6% of NGGCTs, while RAS mutations were present in 20% of germinomas and 3% of NGGCTs." (PMID 38790424, 2024). "The expression of the KIT protein was detected in germinoma and more than half of NGGCTs, suggesting that upregulation of the MAPK pathway plays a central role in most IGCTs." (PMID 36158643, 2022). "In a cohort of 54 germinomas, hypomethylation and KIT staining by immunohistochemistry were detected in 100% of the cases, underlining the resemblance to primordial germ cells." (PMID 34357128, 2021). "The first type possessed activating KIT mutations and fewer copy number alterations, suggesting that the activation of the KIT pathway was essential for some germinomas." (PMID 32999426, 2020). "Unlike the more frequent alterations observed in the KIT/RAS pathway in germinomas, the occurrence rate of mutations in the AKT/mTOR pathway was similar between germinomas and NGGCTs." (PMID 38790424, 2024). "In another study, after dissecting and analyzing the mutation features of the various pathological components of mixed GCTs, it was found that the germinoma component and NGGCT component shared common KIT/RAS mutation characteristics but with different levels of methylation." (PMID 38790424, 2024). "Furthermore, in the cohort, among the three cases of NGGCTs with KIT or RAS mutations, two were mixed GCTs with combined germinoma components." (PMID 38790424, 2024). "Furthermore, somatic mutations in KIT and RAS genes were identified and found to be “mutually exclusive” in most germinomas." (PMID 37036624, 2023). "However, regardless of the KIT mutation status, almost all germinomas showed positive expression in immunohistochemistry (IHC) for KIT, and approximately half of NGGCTs also exhibited KIT-positive expression in IHC." (PMID 38790424, 2024).
germinoma (continued). "However, the expression levels of KIT were similar between the two types of germinomas." (PMID 32999426, 2020). "Recurrent mutations have been detected in the MAPK or PI3K pathways, most typically in KIT and MTOR and low genome-wide methylation has been demonstrated in germinoma; this most likely reflects the cell-of-origin primordial germ cells for this tumor type." (PMID 36132131, 2022). "The most frequent genes involved in the pathogenesis of these tumours are the KIT and RAS genes, encountered in up to 40% and respectively 34.6% of germinomas." (PMID 34357128, 2021). "KIT expression is of particular interest, as it is seen in the majority of pure germinoma and not seen among NGGCT without germinomatous component." (PMID 39959669, 2025). "Based on our results, we suggest that KIT, TNFRSF8, and ERBB4 may be suitable targets for the treatment of germinoma, ECs, and YSTs, respectively." (PMID 32999426, 2020). "However, it has been widely accepted that germinoma is a prototype of all GCTs, by CSC markers of Oct4, Nanog, SOX17 (germinoma), SOX2 (infantile GCTs), and differentiation markers of PLAP and KIT (germinoma differentiation markers from ES cells, rare in intracranial none germinoma GCTs (NGGCTs))." (PMID 37370764, 2023). "Therefore, alterations in the KIT/RAS pathway may play a more significant role in the pathogenesis of germinomas, and non-mixed subtype NGGCTs may have a lower dependence on KIT/RAS signaling alterations." (PMID 38790424, 2024).
mastocytoma (14 papers, 2009 to 2026). A localized tumor composed of sheets of mast cells without atypia. "Genomic knowledge can be applied to the practice; for example, KIT gene mutations are very often present in mastocytoma cells, which affects disease prognosis." (PMID 38275618, 2024). "The sequencing of exons 8, 9, 11, 13, and 17 in skin biopsies from nine cases of mastocytoma revealed KIT mutations in six cases (three patients with KIT D816V and three patients with internal tandem duplication A502_Y503dup in KIT exon 9)." (PMID 33806685, 2021). "KIT gene mutations in canine mastocytoma occur in 20–30% of cases." (PMID 38275618, 2024). "KIT mutations have also been determined in a few cases of mastocytoma." (PMID 33806685, 2021). "Similarly, murine mastocytoma mast cells (P815) carrying a D814Y mutation in KIT analogous to the human D816V mutation, constitutively produced high levels of IL-6, while normal BMMC did not." (PMID 27611333, 2016). "SHP2 inhibitor II-B08, when combined with Dasatinib, prevented oncogenic KIT signaling and cell growth in human and mouse mastocytoma models in vitro." (PMID 25026279, 2014). "In support of this, we found that mastocytoma cell lines carrying KIT juxtamembrane mutants had IC50 values for masitinib between 10 and 30 nM, whereas in murine primary BMMCs expressing wild-type KIT, the IC50 for masitinib was 200 nM." (PMID 19789626, 2009). "To study the function of SHP2 in KIT-driven SM, we transduced P815 mouse mastocytoma cell line that expresses KITD814Y, with either a non-targeting (NT) shRNA or two separate shRNAs against mouse SHP2." (PMID 25026279, 2014).
acute leukemia (13 papers, 2013 to 2025). A clonal (malignant) hematopoietic disorder with an acute onset, affecting the bone marrow and the peripheral blood. "ISM patients with multilineage KIT D816V mutations have been shown to have a higher risk of progression to AdvSM or acute leukemia than patients with MC-restricted KIT D816V." (PMID 32498255, 2020). "CD117, encoded by the c-KIT protooncogene, is highly expressed at the early stages of hematopoietic development, and in acute leukemia the highest frequency of CD117 expression is found in AML." (PMID 23359050, 2013). "We were able to directly cross-check the clinically most relevant RTK mutations in acute leukemia (i.e. FLT3-ITD, KIT D816V/Y, BCR/ABL1) transfected into an isogenic Ba/F3 background against a panel of leukemic cell lines harboring a corresponding RTK mutation." (PMID 23497317, 2013).
fibrosarcoma (13 papers, 2011 to 2025). A malignant mesenchymal fibroblastic neoplasm affecting the soft tissue and bone. "Both drugs are oral multi-kinase inhibitors that block RAF (rapidly accelerated fibrosarcoma) signaling, as well as vascular endothelial growth factor, platelet-derived growth factor and KIT." (PMID 33809909, 2021). "Recently, the effect of two tyrosine kinase inhibitors (TKI), imatinib (BCR-ABL inhibitor) and masitinib (c-KIT and PDGF inhibitor), on canine fibrosarcoma cells was investigated." (PMID 34944112, 2021). "Additionally, first-generation inhibitors block other targets, such as PDGF receptors (PDGFR), KIT (cluster of differentiation 117: CD117), b-rapidly accelerated fibrosarcoma (RAF), and Fms-like tyrosine kinase 3 (FLT-3), which are not substantially inhibited by axitinib." (PMID 26983443, 2016).
lung adenocarcinoma (13 papers, 2014 to 2025). A carcinoma that arises from the lung and is characterized by the presence of malignant glandular epithelial cells. "Briefly, among newly detected mutations in lung adenocarcinoma, AKT, BRAF, FGFR2, HRAS, and KIT mutations were detected in one sample (1.3%), MAP2K in two samples (2.6%), MET in 4 samples (5.9%), and FGFR3 in 5 samples (7.4%)." (PMID 28404952, 2017). "In addition, EVs from mast cells express and shuttle KIT protein (mast/stem cell growth factor receptor), which in turn promotes tumor growth in recipient lung adenocarcinoma cells by activating the KIT-SCF signaling pathway." (PMID 26649044, 2016). "The results showed that the mRNA expression levels of ESR1, DDX3X, MAPK10, KIT, FOXO1, and MCL1 were significantly lower in both lung adenocarcinoma (LUAD) and lung squamous cell carcinoma (LUSC) tissues (p < 0.001) than normal lung tissues." (PMID 38180107, 2023). "Exosomes from human mast cells activate KIT-SCF signal transduction and accelerate the proliferation of human lung adenocarcinoma cells." (PMID 31799196, 2019).
myelodysplastic syndrome (13 papers, 2014 to 2026). A clonal hematopoietic disorder characterized by dysplasia and ineffective hematopoiesis in one or more of the hematopoietic cell lines. "Nearly all patients with KIT D816V-mutated myelodysplastic syndromes (MDS), MPN, or overlapping MDS/MPN exhibited concurrent SM, whereas 44% of patients with AML and KIT D816V showed evidence of SM at some point in their disease course." (PMID 34063170, 2021).
psoriasis (13 papers, 2012 to 2025). An autoimmune condition characterized by red, well-delineated plaques with silvery scales that are usually on the extensor surfaces and scalp. "KIT mRNA expression level in lesional skin of psoriasis patients was 4.6-fold lower (p < 0.001) and in psoriasis non-involved skin it was 4.2-fold lower (p < 0.001) than in the skin of healthy control subjects." (PMID 34884858, 2021). "However, despite the ability of psoriasis-associated TNF and IL-17 to reduce KIT expression in melanocytes, the number of melanocytes in psoriasis lesional skin is increased." (PMID 34884858, 2021). "Furthermore, a fraction of this cells has been found to express skin homing markers such as CCR10 and cutaneous lymphoid antigen (CLA); therefore, it is proposed that KIT+ ILC2s could migrate to the skin and contribute to chronic inflammation in pathological conditions such as psoriasis." (PMID 34759931, 2021). "As a result, we found that the mRNA expression level of KIT, ENPP3, CMA1, CTSG, TPSAB1 and TPSG1 is decreased in PP compared with PN and NN, indicating the fraction of total mast cells is decreased in psoriasis." (PMID 34887864, 2021).
eosinophilia (12 papers, 2009 to 2025). "Since 60–70% of advSM patients carry a diagnosis of SM-AHN, assessment of histopathologic response of the AHN component will be critical, and has been historically ignored in trials of advSM with KIT inhibitors, with the exception of characterizing peripheral blood monocytosis and eosinophilia." (PMID 33804174, 2021).
lymph node metastasis (12 papers, 2008 to 2025). "At present, there are few data on gene mutation detection in patients with GIST lymph node metastasis reported in the literature, and most of these are KIT exon 11 mutations." (PMID 41105177, 2025). "This study also showed that half of the GIST patients with lymph node metastasis had KIT exon 11 mutations." (PMID 41105177, 2025). "Genetic testing was performed on 45 patients in the lymph node metastasis group, and 33 patients (73.3%) had KIT gene mutations, including 25 patients with KIT 11 mutations and 9 patients with KIT 8 mutations; 12 patients (26.7%) had wild-type GIST, of whom 4 patients had SDHB-deficient GIST." (PMID 41105177, 2025). "In one patient (case 27) the KIT mutation could be detected both in lymph node metastases and in skin metastases." (PMID 19018266, 2008). "In all, 31 out of 35 (89%) primaries, 4 out of 4 (100%) lymph node metastases, 2 out of 2 (100%) skin metastases and 3 out of 3 (100%) local recurrences were positive for c-KIT." (PMID 19018266, 2008). "The association between positive staining for c-KIT and absence of lymph node metastases, absence of associated lesions, and higher survival rates indicates that this is a marker of good prognosis in vulvar cancer." (PMID 22839358, 2012). "Our results show that c-KIT positive cases were associated with absence or involvement of only one lymph node (p = 0.0053) when compared to c-KIT negative cases, which were associated with two or more lymph-node metastasis." (PMID 22839358, 2012). "c-KIT protein was positive by immunohistochemistry in 70.5% of the cases and this was associated with a higher global survival (p = 0.007), a higher recurrence-free survival (p < 0.0001), an absence of associated lesions (p = 0.001), lymph node metastasis (p = 0.0053), and HPV infection (p = 0.034)." (PMID 22839358, 2012). "In 80 consecutive GISTs without lymph node metastases, the IHC examinations were performed using the antibodies CD117 (c-KIT), DOG-1 and c-theta (PKCθ) protein." (PMID 28915565, 2017).
neurofibroma (12 papers, 2007 to 2025). An intraneural or extraneural neoplasm arising from nerve tissues and neural sheaths. "Yang and colleagues showed that heterozygous mast cells were required for neurofibroma development via the c-KIT axis." (PMID 34359780, 2021). "Animal studies also showed that depletion of macrophages by PLX3397, which is a selective colony-stimulating factor-1 receptor (c-Fms) and c-KIT inhibitor that inhibits macrophage and mast cells recruitment, decreased the growth of neurofibroma." (PMID 34359780, 2021). "KIT expression in NB or PCC/PGL (where all three tumors originate from neural crest cells) seems to be higher than in benign neurofibromas or a normal adrenal gland (the most common site of NB localization), but lower than in the embryonic neural tube." (PMID 31681584, 2019). "A KIT inhibitor was used in clinical neurofibroma treatment and clearly relieved neurofibroma burden in some NF1 patients, but other patients failed to respond to treatment." (PMID 31852972, 2019). "Immunohistochemical staining was positive for S-100 but negative for c-KIT, CD34, α-SMA, and desmin; these morphological and immunohistochemical characteristics were consistent with the diagnosis of neurofibroma." (PMID 30178113, 2018). "Immunohistochemical staining was positive for S-100 but negative for c-KIT, CD34, α-SMA, and desmin, and these morphologic and immunohistochemical characteristics were consistent with a diagnosis of neurofibroma." (PMID 30178113, 2018).
neurofibromatosis type 1 (12 papers, 2009 to 2026). A clinically heterogeneous, neurocutaneous genetic disorder characterized by cafe-au-lait spots, iris Lisch nodules, axillary and inguinal freckling, and multiple neurofibromas. "Neurofibromatosis type I-associated GISTs exhibit immunohistochemical expression of KIT, DOG1, and SDHB, frequently present with loss of heterozygosity at 14q and 22q and, occasionally, with KIT mutations and/or mutations in the Notch signaling pathway." (PMID 36900287, 2023). "Although the majority of GISTs are sporadic, there are forms that are associated with a variety of syndromes including Carney-Stratakis syndrome and neurofibromatosis type 1, as well as a subset of familial GIST syndromes that are caused by germline mutations in KIT or PDGFRA." (PMID 26246933, 2015). "Similarly, NF1 gene mutations are commonly seen in neurofibromatosis type 1-associated GISTs and are characterized by a distinct molecular profile lacking KIT or PDGFRA mutations." (PMID 40282558, 2025). "The majority of GISTs are driven by sporadic somatic KIT or PDGFRA mutations rather than inflammation-associated carcinogenesis; rare hereditary and syndromic forms of GIST (e.g., familial KIT/PDGFRA mutations, Carney–Stratakis syndrome, and neurofibromatosis type 1–associated GIST) do exist." (PMID 41517566, 2026).
cervical carcinoma (11 papers, 2017 to 2025). A carcinoma arising from either the exocervical squamous epithelium or the endocervical glandular epithelium. "It has been shown that EPO and SCF may have a synergistic effect on erythropoiesis and migration of cervical cancer cells, and EPOR and KIT may even form a receptor complex." (PMID 35887076, 2022).
liposarcoma (11 papers, 2009 to 2025). A usually painless malignant tumor that arises from adipose tissue. "Expected disease-defining gene alterations were detected in several histological subtypes, including MDM2 and CDK4 in liposarcoma, IDH mutations in chondrosarcoma, and alterations related to tyrosine kinases in GIST (KIT, PDGFR)." (PMID 37542550, 2023).
liver cancer (11 papers, 2017 to 2025). An epithelial or non-epithelial malignant neoplasm that arises from the liver. "Liver cancer organoids (n=7) were also subjected to targeted therapies (KRAS, MET and KIT targeting)." (PMID 33816288, 2021).